ENSG00000285486 (novel transcript)
Gene: Long non-coding RNA gene on chromosome 17 (44,276,368 to 44,281,787, reverse strand). Ensembl gene ENSG00000285486.
Gene Ontology:
Biological process: SRP-dependent cotranslational protein targeting to membrane, signal sequence recognition
Cellular component: signal recognition particle, endoplasmic reticulum targeting